SYK (spleen associated tyrosine kinase)
Diseases named in the same sentence as SYK in open-access papers (continued):
Sharing a sentence is not in itself a finding about the gene and the disease.
breast carcinoma (continued). "However, it has been reported that SYK possesses both tumor promoter and suppressor roles in human breast carcinoma and that decreased expression is associated with a poor prognosis; thus, SYK inhibition may work either synergistically or antagonistically with erlotinib." (PMID 37760847, 2023). "In breast cancer, SYK was involved in the maintenance of the epithelial integrity of the gland via regulating the phosphorylation of β‐catenin and stabilizing the E‐cadherin adherens junction complex." (PMID 37170484, 2023). "About half of them in BL1 and BL2 were overlapping, such as LYN, JAK2, SYK, and EGFR, which were reported to be associated with the aggressiveness of breast cancer, particularly in TNBC." (PMID 36672350, 2023). "The mRNA transport and surveillance pathways also were also particularly enriched in SYK targets in breast cancer cells." (PMID 33670716, 2021). "To this aim, we reconstructed and compared its signaling networks using phosphoproteomic data from breast cancer and Burkitt lymphoma cell lines where SYK behaves as a tumor suppressor and promoter." (PMID 33670716, 2021). "We found that two different sets of signaling pathways are enriched in SYK targets in breast cancer cells and Burkitt lymphoma cells." (PMID 33670716, 2021). "The SYK gene is considered a potent tumor suppressor gene in humans, and its activity increases the suppression of tumorigenicity of breast cancer (BC)." (PMID 34575665, 2021). "In MCF7 and MDA231 breast cancer cells, the SYK targets most commonly found enriched belonged to the actin cytoskeleton regulation and focal adhesion signaling." (PMID 33670716, 2021). "We then selected amongst the identified SYK targets those that showed a major reconfiguration of their interactions in the breast cancer and Burkitt lymphoma SYK networks." (PMID 33670716, 2021). "For instance, SYK ability to regulate the actin cytoskeleton and focal adhesion signaling is much stronger in breast cancer cells." (PMID 33670716, 2021). "In breast cancer cells, the SYK target-enriched signaling pathways included intercellular adhesion and Hippo signaling components that are often linked to tumor suppression." (PMID 33670716, 2021). "To better understand the apparent opposite functions of SYK depending on the cancer type, we and other groups used quantitative phosphoproteomic approaches to identify novel SYK signaling effectors in breast cancer cells." (PMID 33670716, 2021). "In conclusion, this manuscript brings insights into the cell type-specific SYK targets and unveils their signaling networks in breast cancer and Burkitt lymphoma cells." (PMID 33670716, 2021). "A previous study reported fostamatinib, a SYK inhibitor, suppresses chronic lymphocytic leukemia and prevents metastatic recurrence in breast cancer in vivo." (PMID 33712015, 2021). "This allowed us to demonstrate that, in breast cancer cells, the SYK target-enriched signaling pathways included intercellular adhesion and Hippo signaling components that are often linked to tumor suppression." (PMID 33670716, 2021). "SYK anti-oncogenic and anti-invasive activities have been observed using mouse xenograft models of breast carcinoma, pancreatic carcinoma and melanoma." (PMID 33670716, 2021). "In contrast, a number of studies have suggested a negative regulatory role of SYK in the control of cell proliferation, migration and invasion in breast cancer cell lines." (PMID 32292575, 2020). "SYK, therefore, was suggested as a candidate for better diagnosis and treatment of BRCA1 mutation-associated breast cancer." (PMID 32292575, 2020). "Syk expression is downregulated in malignant breast cancer cells, e.g., through hypermethylation of the SYK promoter." (PMID 31817924, 2019). "A tumor-suppressing role for SYK has been demonstrated in e.g. breast cancer, pancreatic cancer, melanoma, hepatocellular carcinoma as well as childhood pro-B-ALL." (PMID 30744170, 2019).
breast carcinoma (continued). "Our results are contrary to the outcomes on breast cancer, in which SYK expression is decreased in patient samples and cells from low grade malignancy to high malignancy." (PMID 29137391, 2017). "SYK ectopic expression in a SYK-negative breast cancer cell line significantly suppresses cell motility and metastatic ability." (PMID 29137391, 2017). "Surprisingly, in a subset of breast cancer cell lines enriched for the basal-like subtype, SYK inhibition impaired viability by reducing STAT3 activity." (PMID 25699542, 2015). "We performed structure activity relationship (SAR) analysis to further support SYK as a critical PKC412 target in breast cancer cells." (PMID 25699542, 2015). "Together, we reveal an unexpected role for the tyrosine kinase SYK in maintaining STAT3 phosphorylation in basal-like breast cancer and provide a rationale for clinically testing SYK small-molecule inhibitors in this subclass of tumors." (PMID 25699542, 2015). "In a previous study, we had analyzed significant expression changes (up or down regulated > = 1.5 fold) following SYK siRNA knockdown in a benign human breast cancer cell line, MCF10A, cultured on a matrix of collagen I." (PMID 24523870, 2014). "There are several reports of tumor suppressor functions for SYK in several solid tumor types, including breast cancer, gastric cancer, and melanoma." (PMID 24564859, 2013). "The spleen tyrosine kinase (SYK) is a tumor/metastasis suppressor gene recently found to be silenced through DNA methylation in breast cancer and T-lineage acute lymphoblastic leukemia." (PMID 18959789, 2008). "There are numerous studies suggesting that SYK (spleen tyrosine kinase) acts as a tumor suppressor in breast cancer and human melanoma as its overexpression inhibits invasiveness of both types of tumors." (PMID 18922183, 2008). "Interestingly, MDH2 overexpression upregulated several genes associated with breast cancer metastasis (IL13RA2, MMP3, PTGS1, SYK, VCAN, and FLT1) and downregulated several genes associated with metastasis suppression (NOTCH3 and HTRA3)." (PMID 41179294, 2025). "In addition to these, several kinases have been linked to breast cancer, including Janus kinase (JAK), tyrosine kinase-like orphan receptor (ROR), and spleen tyrosine kinase (SYK)." (PMID 37711177, 2023). "SYK expression inversely correlates with tumor growth and metastasis in breast cancer." (PMID 33540941, 2021). "To better understand these seemingly contradictory functions, we compared SYK phosphoproteomic data from breast carcinoma and Burkitt lymphoma cells using our in-house Phos2Net bioinformatics tool that reconstructs signaling networks from phosphoproteomic data." (PMID 33670716, 2021). "No mutations were observed in the SYK gene in 201 breast cancer samples (0%) whereas mutations in the PTEN gene were observed in 60 samples from a total of 1097 breast cancer samples (5.5%)." (PMID 32292575, 2020). "Next, we asked if a long-term pharmacologic inhibition of SYK in breast cancer cell lines could lead to an increase in proliferation and EMT/invadopodia markers." (PMID 32292575, 2020). "While the longer SYK variant suppressed breast cancer invasiveness, the shorter variant SYK B did not." (PMID 30744170, 2019). "Previous work reported a tumor-suppressing role for SYK in breast cancer, among others." (PMID 30744170, 2019). "In addition, SYK has been recently recognized as a prosurvival factor in breast cancers, as well as hematopoietic malignancies, representing a strong candidate for anticancer therapy." (PMID 28388297, 2017).
breast carcinoma (continued). "Given that SYK has never been implicated as a drug target in solid tumors and has not been found mutated in breast cancer, we decided to study this interaction further." (PMID 25699542, 2015). "In breast cancer, some studies have suggested a tumor suppressive role of SYK." (PMID 25699542, 2015). "Importantly, these experiments reveal the non-oncogene addiction of a subset of breast cancer cell lines to SYK and thereby identify SYK as a novel and critical breast cancer target." (PMID 25699542, 2015). "Together, this suggests that the role of SYK in supporting or suppressing mammary tumors may be highly context dependent and requires further investigation." (PMID 25699542, 2015). "Confirming our identification of a subset of invasive breast cancers where immune infiltration was indicated by alterations in immune specific mRNAs, we found that the mean SYK mRNA level was higher in the immune enriched subset of cases compared with immune depleted cases." (PMID 24523870, 2014). "Interestingly, all those changes have a clearly anti-metastatic trend - re-expression of GLCE in breast cancer cells MCF7 up-regulates the expression of suppressor genes SYK and NME1 and down-regulates the expression of metastasis marker S1004A and TGFβ." (PMID 20723247, 2010). "The SYK inhibitor, BI 1002494, caused no increase in proliferation in breast cancer cells or primary mammary epithelial cells in 2D or 3D cultures, nor changes in proliferation (CD1/2, CDK4, PCNA, Ki67) or invadopodia markers (MMP14, PARP, phospho-vimentin Ser56)." (PMID 32292575, 2020). "Interestingly, SYK has been implicated in the regulation of cell adhesion and migration, processes related to EMT, and suggested to act as a tumor suppressor in breast cancer." (PMID 25699542, 2015). "However, we demonstrated that heterozygotic SYK is associated with reduction in SYK mRNA compared with diploid cases in breast cancer cases without immune filtration." (PMID 24523870, 2014). "Specifically, we observed up-regulation of genes that drive breast cancer metastasis (IL13RA2, MMP3, PTGS1, SYK, VCAN, and FLT1) and downregulation of metastasis-associated suppressor genes (NOTCH3, and HTRA3)." (PMID 41179294, 2025). "Particularly, in the reconstructed SYK signaling network, the proximal network of YAP1 and STK4, two Hippo pathway proteins, is almost entirely exclusive to breast cancer cells." (PMID 33670716, 2021). "Specifically, we used data obtained from the human breast cancer cell lines MCF7 and MDA231, in which SYK acts as a tumor suppressor, and from the human Burkitt lymphoma cell line DG75, in which SYK plays a pro-oncogenic role." (PMID 33670716, 2021). "Quantitative phosphoproteomics revealed that SYK inhibition abrogates signaling to STAT3, explaining the selectivity for basal-like breast cancer cells." (PMID 25699542, 2015). "Nonetheless, our observations raise the possibility of distinct treatment strategies in SYK-positive SCLC tumors, by analogy to lung tumors overexpressing EGFR, or HER2+ breast cancers, whose response to targeted therapy dramatically improves the outcome." (PMID 24564859, 2013). "SYK, a non-receptor tyrosine kinase, controls breast cancer cell growth and survival and is crucial for B-cell receptor activation." (PMID 37711177, 2023). "In cancer of epithelial origin, SYK is absent in normal breast tissue, benign breast lesions and less malignant breast cancer cell lines." (PMID 29137391, 2017). "This suggests that PKC412-like compounds that do not have the central benzene ring would not be potent SYK inhibitors and hence not display selectivity for the basal-like breast cancer cell lines." (PMID 25699542, 2015).
breast carcinoma (continued). "Evidence of oncogenic activity of SYK in solid tumors, including breast cancer, has not previously been demonstrated, and neither activating nor inactivating SYK mutations have been identified." (PMID 25699542, 2015). "The obtained data indicated that antimitotic effect of D-glucuronyl C5-epimerase in human breast cancer cells in vitro probably is realized mainly via the activation of tumour suppressor genes р53, BRCA1, SYK and E2F1 and change of a balance of pro- and anti-apoptotic factors BCL2, NFKB1 and TNF." (PMID 20723247, 2010). "In summary, the obtained results showed that D-glucuronyl C5-epimerase significantly suppress proliferative activity of breast cancer cells in vitro through the activation of tumour suppressor genes р53, BRCA1, SYK and E2F1 and change of a balance of pro- and apoptotic factors BCL2, NFKB1 and TNF." (PMID 20723247, 2010). "Moreover, there was no breast cancer-exclusive SYK edge, most probably due to the lack of information in the pathway databases on SYK activation in breast cancer cells." (PMID 33670716, 2021). "Although it was composed of target proteins shared by the MCF7 and DG75 cell datasets, the CDK1/SKP1 proximal network had mostly interactions that were exclusive to the breast cancer or DG75 cell network, suggesting that its regulation by SYK could be different depending on the cell type." (PMID 33670716, 2021). "Taken together, these data suggest that up-regulation of the expression of the tumour-suppressor genes (р53, BRCA1, SYK) and transcription factor E2F1 could be responsible for the antimitotic effect of D-glucuronyl C5-epimerase in human breast cancer cells in vitro." (PMID 20723247, 2010).
autoimmune disease (25 papers, 2013 to 2025). A disorder resulting from loss of function or tissue destruction of an organ or multiple organs, arising from humoral or cellular immune responses of the individual to their own tissue constituents. "The pathogenic role of SYK gene variants or related fusion proteins in inflammatory and autoimmune diseases is of wide interest." (PMID 37506139, 2023). "Previous in vivo studies exploring autoimmune diseases have shown that spleen tyrosine kinase (SYK) signalling is involved in the development of pathogenic autoantibody." (PMID 35228550, 2022). "This putative influence on the IFN pathway suggests that targeting of SYK might be beneficial in other IFN‐associated autoimmune diseases, such as Sjogren's syndrome." (PMID 33336508, 2021). "Lanraplenib, a spleen tyrosine kinase (SYK) inhibitor, is being tested for its ability to modulate immune cell signaling in B cells, monocytes, and macrophages, crucial cells in autoimmune disease pathways." (PMID 40095460, 2025). "As a known SYK inhibitor, R788 has been widely used in autoimmune diseases such as rheumatoid arthritis lymphoma and immune thrombocytopenic purpura." (PMID 38443977, 2024). "This review summarizes the mechanisms of SYK‐mediated signal transduction and highlights recent findings on the role of SYK in chronic inflammatory or autoimmune diseases." (PMID 37506139, 2023). "Immune cell receptors, including Fcγ receptors (FcγRs), B‐cell receptors (BCRs), and NK cell receptors, activate SYK through a series of chemical reactions, which then have a vital role in chronic inflammation or autoimmune diseases." (PMID 37506139, 2023). "At the same time, we demonstrate that SYK‐targeted therapy can effectively treat circulatory system, blood system, other inflammatory and autoimmune diseases." (PMID 37506139, 2023). "SYK has for example been implicated in the SLE pathogenesis by regulating T-cell signalling and is suggested as potential target for treatment of autoimmune diseases." (PMID 34605719, 2022). "Spleen tyrosine kinase (SYK) is an essential mediator of immune cell signaling and has been anticipated as a therapeutic target for autoimmune diseases, notably rheumatoid arthritis, allergic rhinitis, asthma, and cancers." (PMID 35846777, 2022). "Accumulating evidence on SYK suggests its potential role in the development of various allergic conditions, autoimmune diseases, and cancer." (PMID 34295919, 2021). "This interpretation is consistent with previous reports that overexpression of Btk transgene led to SLE-like autoimmune disease and expression of SYK, another B cell kinase is increased in B cells from lupus patients." (PMID 34512628, 2021). "In addition, favilipid A inhibited by 58–48% three kinases (JAK3, IKKβ, and SYK) involved in the regulation of the immune system, suggesting a potential use for treatment of autoimmune diseases, hematologic cancers, and other inflammatory states." (PMID 36827099, 2023). "syk targets hematological, autoimmune and other inflammatory diseases and therefore, inhibition of SYK expression or blocking its related pathways may provide new ideas for clinical prevention and treatment of inflammatory or autoimmune diseases." (PMID 37506139, 2023). "SYK acts as an important mediator of the immune response in inflammatory and autoimmune diseases." (PMID 37506139, 2023). "Interestingly, SYK inhibitors were investigated for autoimmune diseases with major B-cell involvement, including rheumatoid arthritis, and the first FDA approval of a SYK inhibitor, fostamatinib was granted for treatment of immune thrombocytopenia (ITP)." (PMID 33363034, 2020). "In this regard, the SYK–BTK axis is an attractive target because it is critical for antigen receptor signaling, abnormal regulation of which has been implicated in the pathogenesis of several autoimmune diseases, including RA and SLE." (PMID 24286216, 2013).
autoimmune disease (continued). "In addition, this work suggests that inhibiting SYK expression or blocking its related pathways may provide new ideas for the clinical prevention and treatment of inflammatory or autoimmune diseases." (PMID 37506139, 2023). "Lanraplenib, a selective spleen tyrosine kinase (SYK) inhibitor, was originally developed to treat autoimmune diseases and cancer." (PMID 40560886, 2025). "In this study, we evaluated the effects of three SYK inhibitors on hepatic IRI: GS-9973, R406, and Piceatannol, which have now been shown to have therapeutic promise in hematologic tumors and autoimmune diseases." (PMID 39261768, 2024). "Similar to SYK inhibitors, BTK inhibitors are also being investigated in autoimmune diseases and some are approved for this purpose as for ITP, multiple sclerosis or graft-versus-host disease (GVHD)." (PMID 33363034, 2020). "Fostamatinib is an inhibitor of spleen tyrosine kinase (SYK), and is currently under investigation for the treatment of several autoimmune diseases." (PMID 32977582, 2020). "Specifically, the spleen tyrosine kinase (SYK, in cluster E), expressed in majority of hematopoietic cells, has been recognized as a therapeutic target in autoimmune diseases such as rheumatoid arthritis." (PMID 28388297, 2017). "Although a variety of drugs targeting SYK have been developed for tumors and autoimmune diseases, the mechanism and specific efficacy of SYK’s role in liver fibrosis are not yet clear." (PMID 34853322, 2021). "Spleen tyrosine kinase (SYK), a non-receptor tyrosine kinase expressed in the cytoplasm, initially identified for its high expression in hematopoietic cells and recognized as a crucial target for the treatment of various autoimmune diseases." (PMID 39261768, 2024). "Considering the importance of SYK in the BCR signaling pathway, these data suggest that mercury can alter BCR signaling in B cells, which might affect B cell responsiveness to self-antigen and have implications with respect to autoimmunity and autoimmune disease." (PMID 28716125, 2017).